TNF (tumor necrosis factor)
Diseases named in the same sentence as TNF in open-access papers (continued):
Sharing a sentence is not in itself a finding about the gene and the disease.
septic shock (62 papers, 2007 to 2026). Shock caused by infection; frequently caused by gram negative bacteria, although some cases have been caused by other bacteria, viruses, fungi, and protozoa; characterized by fever, chills, tachycardia, tachypnea, and hypotension. "TNF-α is one of the most important mediators of endotoxic shock, and it causes pathological conditions such as septic shock by decreasing systemic vascular resistance, increasing cardiac output, and directly reducing the force of cardiac contraction." (PMID 25649890, 2015). "Our previous works showed that ANI markedly reduced TNF-α and IL-1β levels in rats with LPS-induced septic shock." (PMID 38354108, 2024). "Previous animal studies have shown that the P-gp inhibitor verapamil reduces the serum levels of inflammatory mediators (e.g., TNF-α and IL-6) and improves the survival rate of mice upon LPS-induced septic shock." (PMID 36482035, 2023). "In patients with septic shock, decreased monocyte IL-10 production positively correlated with mHLA-DR and tumor necrosis factor-α production." (PMID 36552302, 2022). "Several studies on septic shock have reported that IL-6 and TNF-α levels are elevated and have a correlation between cytokines levels cytokines and mortality." (PMID 34493028, 2021). "Hydrocortisone can reduce the serum levels of pro-inflammatory mediators (TNF, IL-1, IL-6, and IL-8) in patients with septic shock, while inhibiting the activation of endothelial cells (based on the level of soluble E-selectin) and neutrophils." (PMID 34335278, 2021). "In the LPS-induced murine septic shock model used in this study, the levels of IL-6, TNFα, MCP-1, and IL-10 increased 36 h after LPS administration, except IL-1β." (PMID 34066510, 2021). "Patients with septic shock have an increased permeability of the blood-brain barrier due to inflammation (e.g., TNF-α)." (PMID 32456003, 2020). "Continuous venovenous hemofiltration (CVVH) effectively suppresses proinflammatory cytokines, including interleukin (IL)-1β, IL-6 and tumor necrosis factor alpha (TNFα), and has been used to treat multiple organ dysfunction and septic shock." (PMID 32631415, 2020). "For septic shock patients, an overall decrease in induction efficiency was observed for both TNFα and PTX3 at the transcriptional level, the lowest level being reached after 24 h of stimulation, similarly to HV." (PMID 30687307, 2018). "Because septic shock is mediated by proinflammatory cytokines, the serum concentrations of cytokines such as TNF and IL-6 after the administration of LPS were examined." (PMID 29038465, 2017). "In an experimental septic shock model, melatonin has been shown to counteract the rise in pro-inflammatory cytokine levels including IL-12, TNF-α, and interferon-γ, and to induce the production of the anti-inflammatory IL-10." (PMID 28895895, 2017). "The serum concentration of pr-inflammatory mediators, such as IL-6 and TNF-α, were shown to be markedly increased in CIRCI associated with septic shock and TBI." (PMID 24131855, 2013). "In patients with septic shock, TNF-α levels are higher in elderly when compared to younger individuals." (PMID 21573030, 2011). "IL-10 is an anti-inflammatory cytokine, which can modulate TNF-α production and it has been shown that IL-10 down-regulates TNF-α production in models of septic shock." (PMID 17201926, 2007). "In septic shock patients, neutrophil counts, infection biomarkers (C-reactive protein, ferritin, and procalcitonin levels), and cytokines (IL-1β, IL-2R, IL-6, IL-8, IL-10, and TNF-α) increased significantly." (PMID 36845110, 2023). "However, TNFα production by monocytes from septic shock patients was lower through the decreased proportion of secreting monocytes at early time points of 30 minutes and 60 minutes after LPS stimulation." (PMID 34290706, 2021).
septic shock (continued). "The hallmark features of monocyte deactivation, namely decreased HLA-DR membrane expression and impaired TNFα production in response to LPS stimulation, were assessed for circulating monocytes from septic shock patients and compared to those from healthy donors." (PMID 34290706, 2021). "The results indicated that, similar to the effect of MCC950, treatment with carnosol downregulated IL-1β and TNF-α in the LPS-mediated septic shock mouse model in a dose-dependent manner, along with a reduction in the number of peritoneal exudate cells and peritoneal macrophages." (PMID 32312957, 2020). "Indeed, patients with septic shock show high TNF levels in the plasma, and their TNF levels are related to the patients’ outcomes." (PMID 31269748, 2019). "Moreover, Nlrp3+/+ mice injected with LPS displayed a mild systemic inflammatory response characterized by increased concentrations of specific chemokines and cytokines, including IL-1α and TNF, the latter being the prime mediator of the inflammatory response observed in septic shock." (PMID 35993366, 2022). "Finally, TPO may depress cardiac contractility in septic shock, since it inhibits adrenergic receptor signal transduction in myocardiocytes, and cooperates with TNF-α and IL-1β to the cardio-depressant activity exerted in vitro by serum of septic shock patients." (PMID 26963510, 2016). "In patients infected with gram-negative bacteria, high levels of TNF-α lead to an endotoxemic syndrome or septic shock, which can result in intravascular disseminated coagulation, heart failure and death." (PMID 17201926, 2007). "However, in the 1990s, the use of the fusion proteins TNF receptor–Fc and p55 TNF receptor–IgG to antagonize TNF was not shown to reduce the mortality rate of septic shock patients." (PMID 34335278, 2021). "However, in septic shock patients, the correlation between IFNγ and IL-12 (p70) with CETPI, IL-1β, TNF-α, IL-6, IL-8, and IL-10, were not significant." (PMID 36536294, 2022).
Shock (62 papers, 2002 to 2025). The state in which profound and widespread reduction of effective tissue perfusion leads first to reversible, and then if prolonged, to irreversible cellular injury. "Supporting its emerging role as a predictor of adverse outcome, the associated inflammatory cytokines TNF-α, IL-6 and IL-1Ra had significantly higher values in patients with MI complicated with cardiogenic shock than in those with a more favourable evolution." (PMID 35204357, 2022). "TNF-α level was dramatically increased in the serum from patients with multiple causes-induced septic shock, and was positively correlated with disease severity and prognosis." (PMID 33967760, 2021). "Though TNF is important for host antibacterial resistance, the excessive production of TNF by the stimulation of bacterium-derived LPS may typically cause endothelial damage, multi-organ dysfunctions, and septic shock." (PMID 31269748, 2019). "In addition, we showed that d-Gal sensitized WT mice were susceptible to LPS and succumbed from TNF-induced endotoxic shock after 24 hr whereas TNFtm/tm mice survived the endotoxic shock as did the TNF−/− mice." (PMID 18544042, 2008). "Cardiogenic shock is associated with systemic inflammation and multiorgan failure; convincing data were obtained on the correlation between shock severity and elevated levels of highly sensitive C-reactive protein, interleukin-1b, interleukin-6, and tumor necrosis factor alpha." (PMID 38137809, 2023). "Intraperitoneal injection of L. plantarum K8 lysates in LPS-induced endotoxin shock mice alleviated mortality and reduced serum tumor-necrosis factor (TNF)-α, IL-1β, aspartate aminotransferase (AST) and alanine aminotransferase (ALT) levels." (PMID 34072918, 2021). "The traditional understanding was that uncontrolled release of pro-inflammatory mediators (e.g., interleukin (IL)-1, tumor necrosis factor (TNF)-α) would determine adverse clinical outcomes in patients with septic shock." (PMID 29063386, 2017). "It is noteworthy that a previous study showed that in vitro exposure to TNF-α or IL6 isolated from serum of humans with septic shock induced depression of rat cardiac myocyte contractile function, and these two factors appeared to have a synergistic effect." (PMID 26812689, 2016). "We have previously shown that high TPO concentrations in plasma samples from patients with septic shock cooperate with TNF-α and IL-1β in depressing myocardial contractility." (PMID 26963510, 2016). "LPS-induced endotoxic shock in ANXA1–/– mice was also correlated with increase in TNFα, IL-1 and IL-6 levels in the blood when compared with wild-type mice." (PMID 27540524, 2016). "The cytokines, interleukin 1 (IL-1), tumor necrosis factor α (TNFα), and interferon gamma (IFNγ) are pivotal mediators in animal models of superantigen-induced toxic shock." (PMID 25688664, 2015). "In summary, this study revealed the critical involvement of the IL-6/JAK/STAT3, PI3K/Akt/mTOR, and TNF-α/NF-κB pathways in pediatric postoperative septic shock and identified key genes such as PIM3, with quercetin and astramembrannin I predicted as potential therapeutic compounds." (PMID 41189212, 2025). "Furthermore, t-test analyses revealed a decreased proinflammatory cytokine IL-1, while mRNA levels of TNF-α and IL-6 were unaltered by foot-shock." (PMID 39544929, 2024). "It has also been shown that endotoxin-treated volunteers had elevated tumor necrosis factor (TNF) levels, and decreased neutrophil functions when they had taken NSAIDs, and this may also be true in toxin-induced streptococcal shock." (PMID 30225523, 2018). "These experiments indicated that TNF-α mediated fatal bacterial endotoxic shock." (PMID 29850597, 2018). "Therefore, naltrexone may prevent LPS-induced septic shock mortality by indirect inhibition of TNF-α production in vivo." (PMID 28824428, 2017).
Shock (continued). "The period of septic shock onset and progression was marked by progressive decline in IL-6 and MIP-2, and progressive increase in TNF-α and IL-10." (PMID 41155249, 2025). "A powerful neutrophil chemotactic chemokine known as interleukin 8 also plays significant roles in the etiology of ARDS, in addition to tumor necrosis factor (TNF) and IL-1, which are significant contributors to septic shock." (PMID 36601152, 2022). "It was shown that IL-1β, TNF-α, and IFN-γ were below detection limit in patients with septic shock admitted to an ICU." (PMID 28097512, 2017). "These investigators showed that HMGB1 was released by macrophages stimulated by lipopolysaccharide (LPS), tumor necrosis factor-α (TNF- α), and IL-1ß and that high HMGB1 was measured in plasma from patients with septic shock." (PMID 22788849, 2012). "We documented the early time course evolution of circulatory Prdx1, hypoxic marker carbonic anhydrase IX, inflammatory cytokines including IL-6, IL-8, IL-10, MCP-1, TNF-α, IL-1β, and danger signaling receptors (TLR4 and CD14) in a cohort of cardiogenic shock patients within 1 day after ECMO support." (PMID 27142532, 2016). "Similarly, VPA showed protection from lung inflammation by decreasing serum IL-6 and TNF-α levels, as well as MPO activity significantly in pulmonary tissue by amelioration of lung damage in a rat model of septic shock or acute lung injury." (PMID 25938838, 2015). "In addition, the pathogenesis of LPS-induced septic shock has been well described in the literature, with the involvement of the toll-like receptor 4 (TLR4)-dependent inflammatory cascade, resulting in an excessive secretion of TNF-α and interleukins." (PMID 35628471, 2022). "Reduced levels of IL-1β, TNF-α and IL-6 were detected in the NLRC4-siRNA group, compared with the sham and NC-siRNA groups (all pCLP vs. NLRC4-siRNA < 0.001; pNC-siRNA vs. NLRC4-siRNA < 0.001), which suggested that NLRC4 gene silencing alleviated the inflammatory reaction induced by septic shock." (PMID 33406504, 2021). "Moreover, patients with NSTI and septic shock at baseline had significantly higher levels of IL-1β, IL-6, IL-10 and TNF-α level than in patients with NSTI without shock." (PMID 28176831, 2017).
toxoplasmosis (62 papers, 2009 to 2025). A parasitic disease contracted by the ingestion or fetal transmission of toxoplasma gondii. "Intriguingly, following T. gondii infection, the m6A levels of DEGs associated with toxoplasmosis, TNF signaling pathway, and NF-κB signaling pathway were significantly different." (PMID 40663568, 2025). "In contrast to toxoplasmosis, both humans and mice have an increased risk for tuberculosis under anti-TNF treatment, which further highlights the discrepancies between different infections." (PMID 30873157, 2019). "Patients with latent T. gondii infections may be at greater risk for reactivation of toxoplasmosis if they are on anti-TNF-α therapy." (PMID 39959486, 2025). "Our objective was to verify whether patients with autoimmune rheumatic diseases, who use TNF antagonists and/or synthetic drugs and had previous contact with Toxoplasma gondii (IgG+), present any indication of an increased risk of toxoplasmosis reactivation." (PMID 36979909, 2023). "KEGG pathway enrichment analysis showed that DEGs were enriched in TNF signaling pathway, toxoplasmosis pathway, cytokine-cytokine receptor interaction pathway, NF-κB signaling pathway, and so on." (PMID 40663568, 2025). "KEGG pathway enrichment analysis of DEGs with significantly altered m6A modification (FDR < 0.05) after T. gondii infection revealed that such genes were enriched in toxoplasmosis pathway, TNF signaling pathway, NF-κB signaling pathway, and so on." (PMID 40663568, 2025). "We believe that what we have learned about m6A and T. gondii-induced TNF-α production will provide important insights into the pathogenesis of toxoplasmosis and the T. gondii host-pathogen relationship." (PMID 40663568, 2025). "In T. gondii infection, TNF-α synergizes with IFN-γ to play an important role in the protective immunity against toxoplasmosis." (PMID 38276673, 2024). "KEGG analysis showed significant enrichment of infection, neurotransmitter, immunity (Toxoplasmosis, Cytokine-cytokine receptor interaction, NF-kappa B signaling pathway, TNF signaling pathway, etc.)." (PMID 39182245, 2024). "In toxoplasmosis, the treatment with the TNF-α antagonist, etanercept, in mice infected with T. gondii promotes a significant decrease in TNF-α levels which are associated with a higher number of brain cysts." (PMID 36979909, 2023). "It was also observed that pregnant women in the acute phase of toxoplasmosis (IgM+/IgG-) presented higher levels of TNF, IL-1β, IL-2, and IL-12." (PMID 36742306, 2023). "A study has shown that giving honey to toxoplasmosis-infected mice decreased TNF-α mRNA expression but maintained IL-6 mRNA expression." (PMID 36358526, 2022). "Several molecules involved in the immune and inflammatory responses during toxoplasmosis, such as interleukin (IL)-1, IL-23 and tumor necrosis factor alpha (TNFα), can increase MMP production in the brain." (PMID 36104766, 2022). "In the oral animal model for toxoplasmosis, monocytes elicited by T. gondii infection are equipped with several effector mechanisms, including the production of IL-12, secretion of TNF-α, upregulation of MHC class II, and induction of iNOS expression." (PMID 26528819, 2015). "In the course of toxoplasmosis in patients, the level of IL-10 is five-fold higher than that in healthy controls; however, the levels of IL-12 and TNF-α are comparable to those observed in healthy controls." (PMID 24146978, 2013). "Chronic resistance to toxoplasmosis requires a delicate balance between pro-inflammatory cytokines like IFNγ and TNFα to control infection and regulatory cytokines like IL-10 to prevent immunopathology." (PMID 22479310, 2012). "Susceptibility to toxoplasmosis occurred despite upregulation of IFN-γ, TNF-α and NOS2, preservation of IFN-γ-induced microglia/macrophage anti-T." (PMID 21217818, 2010).
toxoplasmosis (continued). "Similar to the studies with Becn1+/− mice, ATG7flox/flox-Lyz-Cre mice were susceptible to toxoplasmosis despite upregulation of IFN-γ, TNF-α and NOS2 mRNA and the generation of T. gondii-specific T cell response." (PMID 21217818, 2010). "In toxoplasmosis, TNF-α appears to be indispensable for macrophage activation and inhibition of parasite replication; however, this is possible only in cooperation with IFN-γ." (PMID 19478959, 2009). "In addition, KEGG pathway enrichment analysis of DEGs with significantly altered m6A modification showed that DEGs in toxoplasmosis pathway, TNF signaling pathway, NF-κB signaling pathway were highly enriched." (PMID 40663568, 2025). "However, during the chronic phase of toxoplasmosis, TNF-α and TNFR play a significant role in maintaining disease resistance and latency." (PMID 36979909, 2023). "In addition to the TNF pathway, we detected enrichment of candidate genes involved in the toxoplasmosis (TGFβ2/CHUK/CIITA/SOCS1) pathway in the tolerant animals." (PMID 35464478, 2022). "The major 10 KEGG pathways were significantly associated with various physiological processes, including NOD-like receptor signaling pathway, Toxoplasmosis, TNF signaling pathway, Proteoglycans in cancer, Ras signaling pathway, NF-kappa B signaling pathway and PI3K-Akt signaling pathway." (PMID 34690779, 2021). "TNF-α and IL-1α are critical for survival during acute murine toxoplasmosis." (PMID 32733463, 2020). "However, although anti-TNF therapy is becoming common, only very few cases of severe toxoplasmosis, reactivated TE or OT have been reported in patients undergoing anti-TNF therapy." (PMID 30873157, 2019). "The effector protein of T. gondii interacting with molecules of the host TNF-α signal pathway should be identified, which may provide new directions for anti-toxoplasmosis drug development." (PMID 29173277, 2017). "Next, we examined whether susceptibility to toxoplasmosis in CD40−/− mice could be explained by impaired expression of IFN-γ, TNF-α and NOS2." (PMID 21217818, 2010). "Additionally, TNF-α could drive the conversion of tachyzoites to bradyzoites, resulting in the transition of toxoplasmosis from acute to chronic phase." (PMID 40663568, 2025). "The three most used types of treatment, corticosteroids, anti-TNF-α and antimetabolites, whether alone or associated, do not promote ocular toxoplasmosis more than other toxoplasmosis forms." (PMID 35939518, 2022). "Thus, in spite of upregulation of IFN-γ, TNF-α and NOS2, and the development of T cell-mediated immunity against T. gondii, mice with defective autophagy and with impaired autophagy protein-dependent killing of the parasite are susceptible to toxoplasmosis." (PMID 21217818, 2010). "Inflammatory monocytes strongly express inducible nitric oxide synthase (iNOS), tumor necrosis factor (TNF)-α, and interleukin (IL)-12 to protect against lethal toxoplasmosis." (PMID 39051675, 2024). "According to the KEGG mapping of the DE mRNAs, most of the top 20 significant signaling pathways were different across the three comparison groups, except for pathway in cancer, tumor necrosis factor (TNF) signaling pathway and toxoplasmosis." (PMID 33479333, 2021). "Patients developing all toxoplasmosis forms had circulating tachyzoites, IFN-γ inhibition and high TNF-α production." (PMID 32126572, 2020). "We found a pattern of increased TNF-α levels and low production of IL-2 and TGF-β production in the congenitally infected newborns, with disseminated toxoplasmosis and an inverse profile in those with localized lesions." (PMID 32231666, 2020). "Induced NO production by macrophages is generally related to cytokines such as IFN-γ and tumor necrosis factor α (TNF-α) which play a vital role in immunity of chicken against coccidiosis and toxoplasmosis." (PMID 30081942, 2018).